ID1 (inhibitor of DNA binding 1)
Diseases named in the same sentence as ID1 in open-access papers (continued):
Sharing a sentence is not in itself a finding about the gene and the disease.
colorectal cancer (24 papers, 2008 to 2025). A primary or metastatic malignant neoplasm that affects the colon or rectum. "Here the authors report that ID1-expressing tumor associated macrophages favor colorectal cancer progression by promoting cancer cell stemness and CD8+ T cell exclusion." (PMID 37996458, 2023). "Knock down of Id1 arrests the growth of colorectal cancer cells and suppressed hepatic metastasis in vivo 82, except for colitis-associated colorectal cancer." (PMID 32410828, 2020). "In this study, high Id-1 expression was significantly associated with high VEGF expression in colorectal carcinomas, which is consistent with the results of the previous studies on different types of tumours." (PMID 19014499, 2008). "This study revealed that Id-1, EGFR and VEGF took part in development and progression of colorectal carcinomas and that Id-1 was associated with regulations of EGFR and VEGF." (PMID 19014499, 2008). "However, Id-1 is also significantly associated with breast, pancreas, cervical, ovarian, and colorectal cancers in humans." (PMID 31250351, 2019). "Furthermore, several genes included in this list have previously been linked to colorectal cancer (i.e. Id1, Lgals9, Stat2, and Dab2)." (PMID 27129739, 2017). "Increased Id-1 expression was associated with high grade and advanced stage colorectal carcinomas, which suggested that Id-1 could be used as a prognostic indicator." (PMID 19014499, 2008). "For instance, downregulation of ID1 expression has been shown to mitigate the progression of colorectal cancer and enhance tumour responsiveness to both immunotherapy and chemotherapy." (PMID 40078091, 2025). "Recently, high expression of ID1 in TAMs was correlated with poor outcomes in colorectal cancer patients." (PMID 39676870, 2024). "Here, we report that high expression of inhibitor of differentiation 1 (ID1) in TAMs correlates with poor outcome in patients with colorectal cancer (CRC)." (PMID 37996458, 2023). "ID1 is generally considered an oncogene and has been reported to mediate the stemness of colorectal cancer cells." (PMID 37373188, 2023). "Id1 maintains the stemness of colorectal cancer cells through the Id1-c-Myc-PLAC8 axis through activating the Wnt/β-catenin and Shh signaling pathways." (PMID 32410828, 2020). "Within liver tumors, inhibitor of differentiation 1 (ID1), and within colorectal cancer cells, N-Myc downstream regulated gene 2 (NDRG2), function as suppressors of MYC function that further impact cellular metabolism." (PMID 28362357, 2017). "Knockdown of ID1 has been shown to significantly decrease mRNA and protein levels of survivin in colorectal cancer cells as well as to remove survivin inhibition of apoptosis in head and neck squamous cell carcinoma." (PMID 28582447, 2017). "Emerging evidence indicates that the increased expression of Id1 and Id3 is positively correlated with the self-renewal and tumor-initiation abilities of colorectal cancer-stem cells." (PMID 26965643, 2016). "As far as we know, this is the first study to show that Id-1 expression was significantly associated with EGFR and VEGF in colorectal carcinomas." (PMID 19014499, 2008). "In spite of the widespread involvement of LIF in the STAT3 pathway found in oncological studies, other oncogenic pathways associated with LIF exist, for instance, the LIF/p‐AMPK signaling pathway in HCC, and the LIF/STAT3/ID1/ MDM2 signaling pathway in colorectal cancer." (PMID 40416597, 2025). "Inhibitor of Differentiation 1 (ID1) is an oncogene for colorectal cancer." (PMID 33990575, 2021). "Higher Id1 expression in colorectal cancer specimens than in normal mucosal specimens was shown and high Id1 expression positively correlated with poor differentiation in colorectal cancer." (PMID 32410828, 2020).
colorectal cancer (continued). "In addition, overexpression of ID1 in the primary cancer cells relative to normal mucosa has been observed in primary human oesophageal and colorectal cancers." (PMID 19491902, 2009). "There have been few studies showing the role of Id-1 in colorectal carcinoma." (PMID 19014499, 2008). "Although it is still debatable whether angiogenesis affects advanced colorectal carcinomas, we found that increased angiogenesis, shown by VEGF, contributed to tumour progression and that Id-1 was associated with VEGF in colorectal carcinomas." (PMID 19014499, 2008). "Id1 proteins detected by IHC may show increased expression in colorectal cancer and mouse models, and one now retracted report proposed that a genetic knock-out of Id1 results in adenoma suppression in the small intestine of ApcMin/+, but not when colitis is chemically induced." (PMID 40348815, 2025). "However, there have been few studies on the role of Id-1 in colorectal carcinoma." (PMID 19014499, 2008). "ID1 promoted the stemness phenotype through the activation of the WNT/SHH signaling pathway in brain and colorectal cancer." (PMID 37759448, 2023). "The finding that Id-1 plays a role in the EGFR pathway, an alternative likely to be used in advanced colorectal cancers, indicates a new therapeutic target." (PMID 19014499, 2008). "The finding that Id-1 had effects on the molecules EGFR and VEGF in colorectal carcinomas is important in that these two molecules have been considered as new therapeutic targets for many advanced tumours recently." (PMID 19014499, 2008). "SMAD4, ID1, SPP1 and PAK3 mRNA expression also appeared to have prognostic implications for colorectal cancer using the TCGA cohorts, and with further evaluation required in extended human cohorts, are candidate functional readouts associated with disruption of the TGF-β-BMP-SMAD4 pathway." (PMID 40348815, 2025). "In addition, treatment with CM from M1-like RAW 264.7 cells in an orthotopic colorectal cancer model increased CD8+ T cell infiltration in the tumor, which was abrogated by Id1 overexpression." (PMID 37996458, 2023). "Silencing of ID1 impaired CSC-like capability and inhibited EMT traits in colorectal cancer." (PMID 32547321, 2020). "Interestingly, the proteins ASCL2 and ITF-2B as well as ID1 and ITF-2B are known to interact with each other, suggesting that these bHLH proteins form a functional network in colorectal carcinoma cells." (PMID 24467841, 2014). "However, to our knowledge, this study was the first to show a relation between Id-1 and EGFR and VEGF in colorectal cancers." (PMID 19014499, 2008). "The aim of this study was to reveal whether there was a relationship between Id-1 and EGFR and VEGF in colorectal carcinoma." (PMID 19014499, 2008). "Tumour and non-tumour tissue specimens from 46 cases of colorectal carcinoma were exposed to immunohistochemical staining for Id-1, EGFR and VEGF." (PMID 19014499, 2008). "Furthermore, ID1, but not ID3 expression, was also found to be on average threefold higher (and up to ninefold higher) in PBMCs from patients with metastatic breast cancer (n=7) and colorectal cancer (n=6) compared with healthy, age-matched controls (n=10, Mann–Whitney test; P<0.01)." (PMID 25924227, 2015).
pancreatic cancer (24 papers, 2004 to 2025). "Overexpression of ID2 in pancreatic cancer cells promotes cancer cell growth, while ID1 is linked to increased tumor angiogenesis in pancreatic cancer." (PMID 38195969, 2024). "The overexpression of ID1 has been linked to various types of cancer, including leukemia, breast and pancreatic cancer." (PMID 37505532, 2023). "The authors concluded that increased ID1 expression might be associated with the enhanced proliferative potential of pancreatic cancer cells." (PMID 36627902, 2022). "Also Id1 has been found to be overexpressed in human pancreatic cancers, which is associated with enhanced tumor angiogenesis but not with poor prognosis." (PMID 28122577, 2017). "In a recent study of pancreatic cancer, increased ID1 expression was associated with increased MVD." (PMID 16189525, 2005). "Moreover, cDNA microarray analysis indicates water eluate treatment causes a changed gene expression pattern in pancreatic cancer cells, among which the subsequent analysis demonstrates ID1 is critically involved in cell growth arrest of pancreatic cancer resulted by the dark tea extract." (PMID 31777585, 2019). "Reduced expressions of Id-1 and Id-3 have been demonstrated to inhibit the metastatic ability of gastric cancer cells, and Id-1 expression has been shown to be associated with the presence of invasion in endometrial carcinoma and tumour angiogenesis in human pancreatic cancer." (PMID 18000500, 2007). "To further investigate the mechanism by which ID1 promotes pancreatic cancer growth under hypoxic conditions, we first examined ID1 protein expression following hypoxia treatment." (PMID 40919143, 2025). "Consistent with tissue analysis, elevated ID1 expression was also observed in multiple human pancreatic cancer cell lines, including AsPC-1, PANC-1, and SW1990, compared with normal human pancreatic duct epithelial cells (HPDEC)." (PMID 40919143, 2025). "Together, these data establish that hypoxia stabilizes ID1 by specifically impairing its ubiquitin-proteasomal degradation, revealing a post-translational mechanism for ID1 accumulation in pancreatic cancer." (PMID 40919143, 2025). "Another study in pancreatic cancer showed ID1 uncouples TGFβ-induced EMT from apoptosis leading to enhanced cell survival." (PMID 36627902, 2022). "The ID1 gene has been previously shown to be upregulated in pancreatic cancer cells following nicotine stimulation via a Src kinase-dependent fashion leading to chemoresistance to gemcitabine treatment." (PMID 36627902, 2022). "In our analysis of the TCGA database, we found that ID1 expression was highly expressed in pancreatic tumor samples compared to normal pancreas tissue." (PMID 36627902, 2022). "Enforcement of ID1 expression has previously been reported to play an important role in circumventing Tgf-β’s tumor-suppressive effect in pancreatic cancer." (PMID 34031428, 2021). "More recently, Id1 has been shown to repress TGF-β-induced apoptosis signaling in pancreatic cancer." (PMID 33126649, 2020). "K-Ras mutant pancreatic cancers with intact transforming growth factor-β (TGF-β) pathway drive tumor growth via ID1." (PMID 32516941, 2020). "An arabinogalactan polysaccharide from the Panax notoginseng (RN1) has been able to inhibit microvessel formation in pancreatic cancer-cell xenograft tumors in nude mice through the inhibition of BMP2/Smad-induced Id1 expression." (PMID 28122577, 2017). "Some of the proteins, such as IL10, ID1 and IL2, had been implicated as possible biomarkers of pancreatic cancer before." (PMID 28060763, 2017). "For example, Id1 and Id2 are both over-expressed in pancreatic cancer cells, and are both considered prognostic markers of squamous cell carcinoma metastasis in the esophageal region." (PMID 23517130, 2013). "In conclusion, our findings demonstrate the role of Id-1 overexpression in human primary pancreatic cancer." (PMID 15026801, 2004).
pancreatic cancer (continued). "As a positive association of Id-1 expression with tumour angiogenesis, we examined the effect of Id-1 expression upon clinicopathologic prognostic factors in pancreatic cancer patients." (PMID 15026801, 2004). "Id-1 was also found to be overexpressed in pancreatic cancers and in dysplastic/metaplastic ducts in chronic pancreatitis." (PMID 15026801, 2004). "Finally, ubiquitination assays in TRIM21-knockdown cells revealed that TRIM21 ablation significantly attenuated ID1 ubiquitination, supporting its role as a critical E3 ligase for ID1 degradation in pancreatic cancer cells." (PMID 40919143, 2025). "Furthermore, elevated ID1 was shown to correlate with worse overall survival in resected pancreatic cancer patients." (PMID 36627902, 2022). "It is predicted that ID1 dependent pancreatic cancers could be sensitive to specific ID1 small-molecule inhibitors." (PMID 32516941, 2020). "Similarly, the combined inhibition of Id1 and Id3 in human pancreatic tumor cells resulted in decreased ability of pancreatic cancer cells to proliferate and migrate." (PMID 23311395, 2013). "However, our data show that no significance between Id-1 overexpression and the clinicopathological biomarkers, such as survival rate, stage and tumour grade although Id-1 overexpression is related with tumour angiogenesis in pancreatic cancers." (PMID 15026801, 2004). "Thus, in the present study, we examined the proliferative potential of Id-1 expression in human primary pancreatic cancer by investigating the relation between its expression and the cell kinetic indices of PI and AI." (PMID 15026801, 2004). "Therefore, we undertook to examine Id-1 overexpression in human pancreatic cancers to determine its role as a poor prognostic factor." (PMID 15026801, 2004). "Id-1 overexpression was found to be closely related to tumour angiogenesis, a higher density of intratumoral vessel, but not with a poorer survival or a higher cell proliferation potential in human pancreatic cancer." (PMID 15026801, 2004). "Notably, hypoxia further enhanced the pro-proliferative effects of ID1 in pancreatic cancer cells." (PMID 40919143, 2025). "Furthermore, it underscores the intimate interplay between microenvironmental cues and key oncogenic regulators like ID1, which may collectively drive tumor growth, progression, and therapeutic resistance in pancreatic cancer." (PMID 40919143, 2025). "Finally, we assessed the ubiquitination of ID1 in pancreatic cancer cells." (PMID 40919143, 2025). "Moreover, the transcription of ID1 was found to be repressed by water eluate fraction, and its downregulation was required for dark tea extract or/and p38 inhibition-suppressed growth of pancreatic cancer cells." (PMID 31777585, 2019). "In an orthotopic mouse model of pancreatic cancer using a metastatic L3.6pl cell line, nicotine could enhance not only tumor growth but also metastasis to the liver; this effect could be abrogated by depletion of ID1." (PMID 26264026, 2015). "Similarly, other studies have shown that simultaneous targeting of Id1 and Id3, compared to targeting of each gene alone, is more effective at inhibiting tumor growth and metastatic potential of breast, colorectal, gastric, and pancreatic cancers." (PMID 19956687, 2009). "To investigate the association between Id-1 expression and cell proliferation or tumour angiogenesis, we examined the cell cycle kinetic indices (the proliferation and apoptotic indices, PI and AI) and intratumoral microvessel density (MVD) in 65 human pancreatic cancers." (PMID 15026801, 2004). "Thus, it has been suggested that Id-1 is one of the early markers in pancreatic malignant transformation and that it may contribute to the early step carcinogenesis of human pancreatic cancer." (PMID 15026801, 2004).
pancreatic cancer (continued). "In conclusion, hypoxia-induced downregulation of TRIM21 stabilizes ID1 and promotes pancreatic tumor progression, highlighting the TRIM21–ID1 pathway as a promising therapeutic target for pancreatic adenocarcinoma." (PMID 40919143, 2025). "In vivo, ID1 silencing impeded, while TRIM21 knockdown accelerated, pancreatic tumor growth, confirming their opposing roles in tumor progression." (PMID 40919143, 2025). "Our findings demonstrate that hypoxia drives pancreatic tumor progression by downregulating TRIM21, leading to stabilization of the oncogenic protein ID1." (PMID 40919143, 2025). "Depletion of Id1 in BMDM-derived TAMs also inhibited tumor growth of liver cancer and pancreatic cancer, decreasing the tumor stem cell proportion and promoting the infiltration and activity of CD8+ T cells." (PMID 37996458, 2023). "While Id1 downregulation was deleterious to cells derived from pancreatic tumors that retained functional TGF-β pathway, they were protected from apoptosis when Id1 was dysregulated and SOX4 expression was decreased." (PMID 33126649, 2020). "Knockdown of ID1 and ID3 inhibited metastatic potentials of esophageal and pancreatic cancers in vitro and in vivo." (PMID 23768125, 2013). "The role of ID1, ID2 and ID3 are expected to be oncogenic due to their overexpression in pancreatic cancer and colorectal adenocarcinomas, respectively." (PMID 18513385, 2008). "ID1, ID2 and ID3 are overexpressed in several human tumour entities, e.g. pancreatic cancer and colorectal adenocarcinomas." (PMID 18513385, 2008). "K-Ras pancreatic cancers with active TGF-β pathways (50%) upregulate the Snail family transcriptional repressor 1 (SNAIL), thus repressing KLF5 expression and, in parallel, activating AKT switch ID1 regulation by TGF-β from repression into induction." (PMID 32516941, 2020). "Nevertheless, our results suggest that Id-1 overexpression does not have greater influence on the prognosis of human pancreatic cancer than other important prognostic markers, including stage and tumour grade." (PMID 15026801, 2004). "Our data indicate that Id-1 expression is closely related with tumour angiogenesis, but that it is not related to a poorer prognostic marker in human pancreatic cancers." (PMID 15026801, 2004). "However, our data show no significant relation between Id-1 expression and tumour cell proliferation in human primary pancreatic cancers." (PMID 15026801, 2004).